NBR2 (neighbor of BRCA1 lncRNA 2)
Synonyms: NCRNA00192
Gene: Long non-coding RNA gene on chromosome 17 (43,125,420 to 43,153,671, forward strand). Ensembl gene ENSG00000198496.
Diseases named in the same sentence as NBR2 in open-access papers:
NBR2 is named in the same sentence as 25 diseases in open-access papers, as found by Europe PMC text mining. Sharing a sentence is not in itself a finding about the gene and the disease. The quoted sentences say what the papers report.
breast carcinoma (4 papers, 2018 to 2022). "Similar to BRCA1, the potential application of NBR2 as a cancer biomarker was initially revealed in breast cancer, as the expression of NBR2 decreased in primary cancer cells derived from human breast cancer tissues." (PMID 34926299, 2021). "In light of these observations, we may hypothesize that SNPs found to be associated with increased NBR2 expression could be associated with downregulation of BRCA1 and hence with breast cancer risk." (PMID 35333900, 2022).
colorectal cancer (4 papers, 2021 to 2022). A primary or metastatic malignant neoplasm that affects the colon or rectum. "In colorectal cancer, the low NBR2 level has been reported in tumor tissues, and decreased NBR2 expression is associated with the progression of clinical stages." (PMID 34926299, 2021). "The expression of miR-21, which is a cancer promoter, is increased in colorectal cancer tissues and inversely correlated with the NBR2 level." (PMID 34926299, 2021). "Our findings indicated that the lncRNA NBR2 might suppress the progression of colorectal cancer in vitro and in vivo by regulating the polarization of TAM, which could be developed as an important biomarker for the diagnosis and treatment of clinical CRC." (PMID 34506209, 2021). "Treated by curcumin, Lnc NBR2, Lnc KCNQ1OT1, Lnc PANDAR, and Lnc CCAT1 could prove to be potentially effective target molecules in the treatment progress of colorectal cancer." (PMID 36291546, 2022). "In colorectal cancer (CRC), the NBR2–AMPK pathway is involved in curcumin-mediated CRC progression." (PMID 34926299, 2021). "Moreover, NBR2 overexpression inhibits miR-21 expression in colorectal cancer cells and attenuates colorectal cancer cell migration and invasion, whereas miR-21 has no influence on NBR2 expression." (PMID 34926299, 2021).
ovarian carcinoma (4 papers, 2013 to 2024). A malignant neoplasm originating from the surface ovarian epithelium. "The deletion of the NBR2 gene has been reported to be associated with the susceptibility of breast and ovarian cancers in different populations." (PMID 34926299, 2021). "However, it has been demonstrated that the deletion of the NBR2 gene may be closely related to the susceptibility of breast and ovarian cancers in different populations." (PMID 34926299, 2021). "In contrast to the expression of lncRNAs in HGSCs in this study, the expression of ACTA2‐AS1 and NBR2 has been reported to be upregulated in ovarian cancers." (PMID 38571514, 2024). "Subsequent studies further confirmed this finding and showed that low NBR2 expression correlates with poor clinical outcomes in breast and ovarian cancer patients." (PMID 34926299, 2021). "In consideration of the high mutation/deletion rate of the BRCA1 gene in human breast and ovarian cancers, the NBR2 gene, which is proximal to the BRCA1 gene, was initially presumed to be co-deleted/mutated with BRCA1 in certain cancers." (PMID 34926299, 2021). "In addition to breast and ovarian cancers, dysregulated NBR2 expression and function have also been observed in some other solid tumors." (PMID 34926299, 2021). "In a single-strand conformation polymorphism (SSCP) analysis, it was revealed that the NBR2 gene shows no mutations in both breast and ovarian cancers, suggesting that the involvement of the NBR2 gene in these cancers is not concerned with gene mutations." (PMID 34926299, 2021). "A deletion affecting BRCA1, NBR1, and NBR2 at 17q21.31 was identified in a patient with hormone receptor-negative BC with a family history of ovarian cancer (family 252)." (PMID 23967248, 2013).
hepatoblastoma (3 papers, 2021 to 2024). Hepatoblastoma (HB) is a malignant hepatic tumor and is the most common pediatric liver cancer. "The deficiency of NBR2 suppresses the invasion, migration, and viability of hepatoblastoma cells cultured under normal conditions, and facilitates cell apoptosis under glucose starvation." (PMID 34926299, 2021). "TCF7 has been reported to be co-expressed with NBR2, and NBR2 deficiency leads to decreased TCF7 expression in hepatoblastoma cells, along with the down-regulation of the TCF7 protein that is involved in cell cycle progression, glucose entrapment, and epithelial-mesenchymal transition (EMT)." (PMID 34926299, 2021). "NBR2 expression is significantly increased in hepatoblastoma tissues, and glucose starvation is required for this up-regulation." (PMID 34926299, 2021). "It has been reported that the NBR2 level is significantly increased in hepatoblastoma tissues, where it aggravates hepatoblastoma cell malignancy under conditions of glucose starvation through the miR-22–TCF7 axis." (PMID 34926299, 2021). "Furthermore, although NBR2 is downregulated in most cancers, it is upregulated and promotes cell proliferation, migration, and invasion in glioma and hepatoblastoma." (PMID 38571514, 2024). "Consistently, NBR2 has recently been identified to aggravate hepatoblastoma cell malignancy." (PMID 34926299, 2021). "TCF7 has been defined as the target molecule of miR-22 and NBR2, which is localized in both the cytoplasm and nucleus, aggravates hepatoblastoma cell malignancy by sponging miR-22 under conditions of glucose starvation, thereby counteracting miR-22-induced TCF7 repression." (PMID 34926299, 2021). "Similarly, research has identified that lncRNAs TUG1, HOXA-AS2, OIP5-AS1, ZFAS1, SNHG9, NBR2 and MIR205HG are significantly upregulated in HB cells and enhance cell proliferation, migration or invasion in hepatoblastoma." (PMID 38390281, 2024).
hepatocellular carcinoma (3 papers, 2021 to 2024). A malignant tumor that arises from hepatocytes. "It has been demonstrated that in hepatocellular carcinoma (HCC) patients at advanced clinical stages, the overall survival of cases with low NBR2 expression is significantly worse compared to those with high NBR2 expression." (PMID 34926299, 2021). "LncRNA NBR2 can repress autophagy-induced cell proliferation and down-regulate ERK and JNK signals in hepatocellular carcinoma (HCC), thereby inhibiting the malignant progression of HCC." (PMID 39030557, 2024).
glioma (2 papers, 2021 to 2024). A benign or malignant brain and spinal cord tumor that arises from glial cells (astrocytes, oligodendrocytes, ependymal cells). "A recent study has also confirmed that NBR2 promotes the proliferation of glioma cells by inhibiting p15 expression." (PMID 34926299, 2021).
hypertrophy (2 papers, 2022). Hypertrophy is the increase in the volume of an organ or tissue due to the enlargement of its component cells. "Our study provides the first evidence that lncRNA NBR2 is positively associated with myocardial hypertrophy." (PMID 35703318, 2022). "What’s more, overexpressed NBR2 hindered Ang II–induced myocardial hypertrophy, as evidenced by declined ANP, BNP, and β-MHC mRNA levels (vs. the Vector group)." (PMID 35703318, 2022). "Interfering with the LKB1/AMPK/Sirt1 axis abated the lncRNA NBR2-mediated inhibitory effect on myocardial hypertrophy and ER stress." (PMID 35703318, 2022). "Here, we explored the role and mechanism of a novel lncRNA, NBR2, in modulating angiotensin II (Ang II)-induced myocardial hypertrophy." (PMID 35703318, 2022). "In general, NBR2 was distinctly down-regulated in Ang II–induced myocardial hypertrophy, confirming its vital role in myocardial hypertrophy." (PMID 35703318, 2022). "Overall, this study revealed that NBR2 contributes to Ang II–induced myocardial hypertrophy." (PMID 35703318, 2022). "To ascertain whether lncRNA NBR2 contributed to myocardial hypertrophy, we treated HCM and AC16 cells with Ang II to simulate an in-vitro model of myocardial hypertrophy." (PMID 35703318, 2022). "Moreover, one study provided the first evidence that NBR2 is relevant with myocardial hypertrophy by finding that NBR2 inhibits endoplasmic reticulum (ER) stress and myocardial hypertrophy by modulating the LKB1/AMPK/Sirt1 pathway." (PMID 36233294, 2022). "In addition, the overexpression experiment of NBR2 was carried out to probe the influence of NBR2 on myocardial hypertrophy." (PMID 35703318, 2022). "However, whether NBR2 can be adopted as a novel therapeutic target for relieving human myocardial hypertrophy remains to be further studied." (PMID 35703318, 2022). "To examine the function of NBR2 in myocardial hypertrophy, we transfected HCM and AC16 with NBR2 overexpression plasmids prior to Ang II stimulation." (PMID 35703318, 2022). "In addition, overexpressing NBR2 facilitated the LKB1/AMPK/Sirt1 profile, thereby alleviating myocardial hypertrophy and ER stress in HCM and AC16 cells." (PMID 35703318, 2022). "However, the role of lncRNA NBR2 in mediating metabolic checkpoints in myocardial hypertrophy has not been fully explored." (PMID 35703318, 2022).
non-small cell lung carcinoma (2 papers, 2021 to 2022). A group of at least three distinct histological types of lung cancer, including non-small cell squamous cell carcinoma, adenocarcinoma, and large cell carcinoma. "Besides, lncRNA NBR2 impedes epithelial-mesenchymal transition (EMT) in non-small cell lung cancer (NSCLC) by modulating the Notch1 pathway." (PMID 35703318, 2022). "In non-small cell lung cancer (NSCLC), the NBR2 level is low in tumor tissues and is correlated with tumor size and prognosis." (PMID 34926299, 2021).
osteosarcoma (2 papers, 2020 to 2021). A usually aggressive malignant bone-forming mesenchymal neoplasm, predominantly affecting adolescents and young adults. "NBR2 has also been identified to function as an EMT suppressor by regulating NOTCH1 at both transcriptional and post-transcriptional levels in osteosarcoma." (PMID 34926299, 2021).
Sepsis (2 papers, 2021 to 2024). Sepsis is defined as life-threatening organ dysfunction caused by a dysregulated host response to infection. "Most of published studies of homolog lncRNAs were related to cancers, and now, more than forty clinical trials associated with lncRNA, including a study of lnc-NBR2 in sepsis, are in process in clinicaltrials.gov." (PMID 34041287, 2021). "Another clinical study from Southeast University investigates the effect and mechanism of lncRNA NBR2 regulating endothelial pyroptosis by targeting GSDMD in sepsis (ClinicalTrials.gov Identifier: NCT04427371)." (PMID 38543885, 2024).
thyroid cancer (2 papers, 2020 to 2021). "However, there is little information on the role of NBR2 in the progression of thyroid cancers (TC)." (PMID 32596161, 2020).
diabetic nephropathy (1 paper, 2018). "A role for lncRNAs XIST and GM4419 was implicated in diabetic nephropathy while alterations in PANDA and NBR2 P21 were linked to cellular senescence, AMPK regulation, and liver fibrosis, respectively." (PMID 30139387, 2018).
kidney cancer (1 paper, 2021). Primary or metastatic malignant neoplasm involving the kidney. "Phenformin induces NBR2 expression in breast and kidney cancer cells, and NBR2 deficiency renders cancer cells more sensitive to phenformin-induced apoptosis." (PMID 34926299, 2021). "Accordingly, the NBR2 level was down-regulated in breast and kidney cancer patients and was negatively correlated with poor prognosis." (PMID 34926299, 2021). "In breast and kidney cancer cells, NBR2 regulates cancer cell sensitivity to phenformin through glucose transporter 1 (GLUT1)." (PMID 34926299, 2021). "Therefore, the feedback mechanism responsible for NBR2–AMPK regulation in both breast and kidney cancer cells under glucose-starvation conditions was revealed." (PMID 34926299, 2021).
lung carcinoma (1 paper, 2022). "LncRNA NBR2 is downregulated in NSCLC patients, and the overexpression of lncRNA NBR2 could inhibit the migration of lung cancer cells (SPC-A1 cells) and the Notch signaling pathways are also suppressed, and the EMT-related genes are also reduced." (PMID 36033435, 2022).
metastatic tumors (1 paper, 2023). "lncRNA regulation occurs throughout tumor development, during the early stages such as SNGH11; in advanced stages, for example, MFI2-AS1; and even in metastatic tumors with both pro- and anti-tumoral effects, such as FTX and NBR2, respectively." (PMID 38132443, 2023).
renal carcinoma (1 paper, 2020). A carcinoma arising from the epithelium of the renal parenchyma or the renal pelvis. "In this study, we found that NBR2 expression was down-regulated in TC tissues and cells, particularly in ATC, extending previous studies in breast and renal cancers." (PMID 32596161, 2020).
type 2 diabetes (1 paper, 2018). "Compared to control subjects, expression levels of lncRNAs in PBMCs from type 2 diabetes patients showed significantly (p < 0.05) increased levels of HOTAIR, MEG3, LET, MALAT1, MIAT, CDKN2BAS1/ANRIL, XIST, PANDA, GAS5, Linc-p21, ENST00000550337.1, PLUTO, and NBR2." (PMID 30139387, 2018). "Compared to control subjects, expression profiling of lncRNAs in PBMCs from type 2 diabetes patients showed significantly (p < 0.05) increased levels of HOTAIR, MEG3, LET, MALAT1, MIAT, CDKN2BAS1/ANRIL, XIST, PANDA, GAS5, Linc-p21, ENST00000550337.1, PLUTO, and NBR2." (PMID 30139387, 2018).
tumor (21 papers, 2018 to 2026). "Indeed, the NBR2 gene encodes a long noncoding RNA that suppresses tumour development through regulation of adenosine monophosphate‐activated protein kinase activation." (PMID 39783935, 2025). "Previous studies have demonstrated that lncRNA NBR2 acts as a tumor suppressor in HCC by inhibiting cytoprotective autophagy, thereby suppressing tumor growth." (PMID 40789840, 2025). "Subsequent studies confirmed NBR2’s identity as a lincRNA and have begun to elucidate its intricate roles in tumor biology, revealing its involvement in tumor suppression alongside BRCA1." (PMID 39997609, 2025). "Studies have shown that lncRNA NBR2 reduces tumor expansion and metastasis by regulating the polarization of fibroblasts." (PMID 40149989, 2025). "The downregulation of NBR2 correlates with tumor progression, suggesting its potential anti-tumor role in regulating the polarization." (PMID 40149989, 2025). "LncRNA NBR2 inhibits tumor development by regulating autophagy in HCC, and lncRNA CASC9 activates autophagy-mediated cell death by AKT/mTOR pathway." (PMID 36072894, 2022). "Induced lncRNA NBR2, in turn, interacts with AMPK and potentiates AMPK kinase activation, forming an NBR2-AMPK feedforward loop that contributes to tumor growth." (PMID 35842651, 2022). "Depletion of NBR2 leads to unchecked cell cycling, altered apoptosis response, and enhanced tumor development." (PMID 35842651, 2022). "The function of the lncRNA NBR2 in regulating M1 polarization and the anti-tumor efficacy of the lncRNA NBR2 was investigated and confirmed by establishing the lncRNA NBR2 overexpressed and knocked down CRC cells." (PMID 34506209, 2021). "NBR2 was initially identified as a tumor suppressor similar to BRCA1, and plenty of evidence has verified this perspective." (PMID 34926299, 2021). "The lncRNA NBR2 was found to be significantly downregulated in the isolated tumor tissues from CRC patients compared to the para-carcinoma tissues (**P < 0.01, vs. Control)." (PMID 34506209, 2021). "Among these lncRNAs, NBR2 is a newly defined lincRNA whose expression is induced by energy stress in the tumor microenvironment (TME) and participates in cancer development." (PMID 34926299, 2021). "NBR2 overexpression significantly suppresses TC proliferation, clonogenicity, and invasion as well as tumor growth in vivo, whereas NBR2 knockdown has the opposite effects." (PMID 34926299, 2021). "Curcumin, which exists in the rhizomes of Curcuma longa, has been approved for the treatment of CRC, and it can inhibit tumor occurrence by inducing the expression of a suppressor lncRNA neighbor of BRCA1 gene 2 (NBR2)." (PMID 34778084, 2021). "The tumor growth of CRC cells in the nude mice xenograft model was significantly promoted in the lncRNA NBR2 knockdown group, accompanied by an increase in the proportion of M2 macrophages in the tumor tissues." (PMID 34506209, 2021). "A previous study indicated that the lncRNA NBR2 is an important mediator involved in the anti-tumor effects of curcumin by activating the adenosine monophosphate-activated protein kinase and inactivating mTOR signaling." (PMID 34506209, 2021). "In the present study, we suspected that the lncRNA NBR2 functions as a tumor suppressor in CRC development." (PMID 34506209, 2021). "The present study aimed to explore the regulatory function of the lncRNA NBR2 on tumor-associated macrophage (TAM) polarization and its consequent anti-tumor effect." (PMID 34506209, 2021). "Functionally, NBR2 acted as a tumor suppressor to inhibit the malignancy of TC in vitro and in vivo." (PMID 32596161, 2020). "We found that the NBR2 expression was variable in TC tissues and significantly lower than that in non-tumor thyroid tissues (P < 0.05)." (PMID 32596161, 2020). "In this treatment with phenformin, lncRNA NBR2 has been discovered to have a potential role in the adaptive response of tumor cells." (PMID 31850189, 2019).
tumor (continued). "NBR2 functions as a tumor suppressor in human breast and renal cancer." (PMID 35842651, 2022). "We suspected that the lncRNA NBR2 functions as a tumor suppressor in the development of CRC." (PMID 34506209, 2021). "Furthermore, it reveals the opposite role of lncRNA NBR2 in cancer development, which is contrary to the initial view that NBR2 functions as a tumor suppressor." (PMID 34926299, 2021). "Furthermore, a significant inhibitory effect on tumor growth in the nude mice xenograft model was observed in the lncRNA NBR2 overexpressed group, as well as the promotion of M1 macrophage proportion in the tumor tissues." (PMID 34506209, 2021). "Elevated NBR2 expression reduced the apoptosis of tumor cells induced by phenformin." (PMID 31850189, 2019). "NBR2 is also a non-protein coding gene that encodes a long non-coding RNA and suppresses tumor development through regulation of adenosine monophosphate–activated protein kinase (AMPK) activation." (PMID 30594178, 2018). "Ten pairs of tumor and para-carcinoma tissues from 10 CRC patients were collected to check the difference in the lncRNA NBR2 expression levels." (PMID 34506209, 2021). "Depletion of lncRNA NBR2 attenuates energy stress-induced AMPK activation, resulting in unchecked cell cycling, an altered apoptosis/autophagy response, and increased tumor development in vivo." (PMID 33312753, 2020). "Mechanistic studies have revealed that NBR2 inhibits GLUT1 expression and EMT, but promotes AMPK and acetyl-CoA carboxylase (ACC) activation in TC cells, thereby reducing the malignancy of TC and acting as a tumor suppressor." (PMID 34926299, 2021). "While NBR2 silencing significantly enhanced the malignancy of BCPAP cells by increasing cell proliferation, clonogenicity, wound healing, and invasion as well as tumor growth in vivo, and decreasing spontaneous apoptosis, NBR2 over-expression had opposite effects in BHT101 cells." (PMID 32596161, 2020).